BDNF (brain derived neurotrophic factor)
Diseases named in the same sentence as BDNF in open-access papers (continued):
Sharing a sentence is not in itself a finding about the gene and the disease.
depression (continued). "Our scoping review findings support BDNF’s longstanding role as a marker of exercise/PA response since its discovery in 1982 and suggest a potential connection between BDNF changes and symptom improvements, such as reductions in fatigue, pain, and depression." (PMID 40002745, 2025). "First, the absence of a healthy controlgroup limits the ability to fully understand variations in BDNF levels amongolder patients with depression." (PMID 40352065, 2025). "Increasing evidence indicates that BDNF levels are diminished in individuals with depression, and that the BDNF concentrations in peripheral blood are closely associated with the severity of the condition." (PMID 40006068, 2025). "Among men, the most pronounced decreases in BDNF concentrations were found in those with depression and nociplastic pain (−7.02), followed by neuropathic (−5.71) and visceral pain (−5.66) in descending order." (PMID 40222813, 2025). "While certain biomarkers, such as BDNF and VEGF, have already been associated with depression and its treatment, the evidence for other markers remains inconsistent and requires further exploration." (PMID 41149800, 2025). "The outcomes studied included plasma concentrations of NO, depression ratings, brain-derived neurotrophic factor (BDNF), interleukin-1β, interleukin-6, TAC, and MDA." (PMID 41228407, 2025). "It has been suggested that individuals with lower serum levels of BDNF are more prone to developing depression." (PMID 40003622, 2025). "Animal studies have shown that SFN alleviates depression-like behaviors induced by CSDS by enhancing BDNF transcription." (PMID 40949123, 2025). "BDNF ensures neuronal network plasticity, and decreased levels have been observed in cases of depression." (PMID 40724885, 2025). "rTMS can increase cortical monoamine transmitter release, increase glucose metabolism, and increase the level of brain-derived neurotrophic factor (BDNF), which is effective in depression." (PMID 40665248, 2025). "The nutrient‐synbiotic complex presented beneficial effects against the depression‐like behaviors induced by LPS, mitigated the increased level of kynurenine, and decreased levels of 5‐hydroxytryptamine and BDNF both in serum and PFC (p < 0.05)." (PMID 40672547, 2025). "The transcription factor Nrf2 and brain-derived neurotrophic factor (BDNF) play critical roles in depression." (PMID 40149774, 2025). "ANA-12 (TrkB receptor antagonist) - utilised in rodent models to study the role of BDNF in neuroplasticity, depression, and anxiety." (PMID 40097854, 2025). "Imbalances in serotonin can impact BDNF levels, and both contribute to synaptic modulation and neuroplasticity, critical in mood disorders like depression." (PMID 39860451, 2025). "Experiment assessed the effects of tDCS applied to the DLPFC on brain-derived neurotrophic factor (BDNF), depression, anxiety, stress, and craving in opioid-addicted patients undergoing methadone maintenance treatment." (PMID 40004867, 2025). "The HPA axis regulates the stress response and, when overactive, elevates cortisol levels, which can cause atrophy of brain regions crucial for neuronal plasticity and reduce the availability of BDNF, exacerbating depression." (PMID 39981404, 2025). "Regular engagement in such training has been shown to upregulate brain-derived neurotrophic factor (BDNF), a key mediator of synaptic plasticity and neuronal resilience, which is often reduced in individuals with depression." (PMID 40124408, 2025). "Key molecules such as BDNF/5-HT are found restored in animal models, and FC between key brain areas related to depression/anxiety is modulated after LIFU treatment." (PMID 41154223, 2025). "Fibrinogen levels were significantly higher in participants with anxiety and depression, while endocan and BDNF levels were lower in those with anxiety." (PMID 40491453, 2025). "Exercise also increases brain-derived neurotrophic factor, which supports brain health and reduces depression symptoms." (PMID 41662119, 2025).
depression (continued). "A decreased BDNF level in serum was observed in people with mood and eating disorders and depression." (PMID 40656999, 2025). "Further supporting this pathway, several studies have shown a decreased BDNF/proBDNF ratio in patients with depression, suggesting impaired neurotrophin maturation and reduced neurotrophic signaling." (PMID 40725146, 2025). "Administration of Schisandrae chinensis fructus showed a promising therapeutic effect on depression induced by CUMS though activation of BDNF and upregulation of TrkB/CREB/ERK and PI3K/AKT/GSK3β/mTOR signaling pathways." (PMID 40612748, 2025). "Decreased BDNF levels in the cortex and hippocampus of reserpine rat model of depression was observed." (PMID 40522360, 2025). "Collectively, these findings indicate that adiponectin and BDNF fluctuate together in relation to symptom severity, highlighting the central role of neuroplasticity in depression, as will be further discussed in the following section." (PMID 41463298, 2025). "BDNF has attracted attention as a potential mechanistic biomarker for symptom relief, especially in fatigue, pain, depression, and sleep disturbance." (PMID 40002745, 2025). "Our finding in the PPI network for BDNF should be further investigated in future genetic studies, as well as adverse effects, especially in terms of depression and RDS behaviors." (PMID 39865816, 2025). "Clinical studies have shown that BDNF levels are significantly reduced in patients diagnosed with major depressive disorder." (PMID 40697653, 2025). "Studies have shown that brain-derived neurotrophic factor (BDNF) levels are negatively correlated with the severity of depression, and BDNF mRNA expressions can serve as a biomarker for the adjunctive diagnosis of depression." (PMID 40361723, 2025). "WB experiments demonstrated that AEO inhibited the NF-κB/IκB-α inflammatory pathway and activated the BDNF/TrkB/CREB pathway in the hippocampus of the LPS-depression model mice." (PMID 40006068, 2025). "BDNF has emerged as a potential biomarker for depression, with lower serum BDNF levels consistently reported in depressed patients compared to healthy controls." (PMID 40264519, 2025). "Reduced BDNF levels, particularly in the hippocampus and prefrontal cortex, have been observed in individuals with depression and cognitive impairment, suggesting its potential role in managing these symptoms." (PMID 40002745, 2025). "As shown in these sections concerning psychiatric disorders, boosting BDNF function through its specific receptor TrkB is indeed effective in improving symptoms of depression and schizophrenia, as judged by the results from using in vivo and in vitro models." (PMID 40005159, 2025). "Specifically, emerging evidence links altered BDNF trafficking to autism spectrum disorder, schizophrenia, major depressive disorder (MDD), bipolar disorder, Alzheimer’s disease (AD), and Huntington’s disease (HD)." (PMID 41254423, 2025). "This combination significantly reduced depression-like behaviors, demonstrating its potential as a quick-acting antidepressant by altering hippocampus BDNF expression." (PMID 40149774, 2025). "This is accomplished by changing the amount of cyclic AMP (cAMP) and causing the production of Brain-Derived Neurotrophic Factor (BDNF) mRNA, leading to a positive impact on those with Major Depressive Disorder (MDD)." (PMID 40162008, 2025). "Assessments have indicated that hypermethylation of BDNF and NR3C1 is associated with an increased risk of depression, while the methylation profiles of DNMT1/3A, EZH2, and IL-6 correlate to the severity of anxiety." (PMID 39851502, 2025). "Depression severity, cognitive function (Mini-Mental State Examination, Verbal Fluency, Digit Span), and serum BDNF levels were measured pre- and post-treatment." (PMID 40264519, 2025). "Decreased BDNF levels are consistently observed in individuals with depression, and enhancing BDNF signaling is a known mechanism of action for many antidepressants." (PMID 40589649, 2025).
depression (continued). "Plant metabolites of FRG, including ginsenoside Rd and PPT, ameliorate anxiety/depression and colitis via NF-κB-mediated regulation of brain-derived neurotrophic factor (BDNF) expression and GM remodeling." (PMID 40949153, 2025). "While exercise, dietary energy restriction, and cognitive stimulation increase BDNF levels in the hippocampus, adverse conditions including chronic stress, depression, and diabetes suppress BDNF production." (PMID 40649968, 2025). "BDNF has a significant role in the pathogenesis of stress-related diseases, major depressive disorder (MDD), and generalized anxiety disorder (GAD)." (PMID 40728957, 2025). "Conversely, stress-induced elevation of BDNF in the nucleus accumbens promotes depression-like phenotypes, indicating that the spatial regulatory context of BDNF is essential." (PMID 41227125, 2025). "Assessing BDNF levels not only helps understand the pathological mechanisms of depression but also provides new targets for treatment strategies." (PMID 40821647, 2025). "Only three studies examined the mediating effect of BDNF on the effect of exercise/PA on symptoms (depression and cognitive dysfunction) and grouping criteria (high vs. low BDNF groups)." (PMID 40002745, 2025). "For instance, SSA has been shown to alleviate depression-like behavior in cerebral ischemia models by modulating the p-CREB/BDNF axis and inhibiting apoptosis." (PMID 40453654, 2025). "We also explored the antidepressant mechanism of NAc-DBS and found that it exerted antidepressant effects and cognitive improvement in a CUMS-induced depression-like mouse model through the activation of BDNF/AKT/mTOR signaling pathway." (PMID 41234534, 2025). "Apelin alleviates the onset of depression through its function in promoting BDNF production, anti-inflammatory, and anti-oxidative mechanisms." (PMID 41268325, 2025). "Mitochondrial dysfunction affects energy metabolism through its impact on BDNF and related signaling pathways, mediating the occurrence and development of depression." (PMID 40699781, 2025). "The expression level of the 5-HT1A, DRD1, ADRA-2A, GABA-A α1, CNR1, NR3C2, NOD1, NLRP3 and MC4R; BDNF levels, glial activity and intestinal permeability were determined in chronic stress-induced depression in rats." (PMID 40281288, 2025). "BDNF has an important function in the adaptation processes required in depression and has both long- and short-term effects." (PMID 40281288, 2025). "Using optogenetics (a method to control the signaling pathway of cells with light), they discovered a new pathway involving FGFR1, Notch and brain-derived neurotrophic factor (BDNF) proteins that promotes neurogenesis and reduces depression symptoms." (PMID 40813470, 2025). "In mental disorders such as depression, BDNF levels are also considered to be an important biomarker." (PMID 40919224, 2025). "The pronounced reduction in BDNF among depressed patients suggests its potential utility as a biomarker for depression severity in COPD." (PMID 40823578, 2025). "While antidepressants typically elevate BDNF levels, their effect appears to be limited in depression and anxiety symptoms in CUD." (PMID 40943216, 2025). "This scoping review explores the potential role of BDNF as a biomarker in exercise-based intervention for fatigue, pain, depression, and sleep disturbance management." (PMID 40002745, 2025). "This decrease is also reflected in peripheral blood levels, supporting BDNF’s potential as a biomarker for both depression severity and treatment response." (PMID 41149800, 2025). "As a result, it can be anticipated that the communication between Keap1-Nrf2 signaling and BDNF-TrkB signaling in the brain plays an important role in depression." (PMID 40149774, 2025). "In conclusion, this scoping review highlights the limited but notable evidence supporting BDNF as a potential marker for the effectiveness of exercise/PA in managing symptoms such as fatigue, pain, depression, and sleep disturbances." (PMID 40002745, 2025).
depression (continued). "CA upregulates GR expression in the testes, suppresses miR-190b transcription, restores BDNF levels, thereby enhancing neural plasticity and improving depression-like behaviors." (PMID 40949123, 2025). "Vitamin D injection reversed depression-like behavior via ↑ hippocampal BDNF; blocked by TrkB-IgG ↓ anhedonia." (PMID 40871684, 2025). "Hypercortisolaemia also promotes serotonin deficiency and reduces the production of brain-derived neurotrophic factor (BDNF), essential for hippocampal neurogenesis and depression development." (PMID 41375608, 2025). "Probiotics also influence cognitive function by upregulating brain-derived neurotrophic factor (BDNF), increasing monoamine levels, and enhancing neuroplasticity, potentially ameliorating depression." (PMID 39256304, 2025). "In the multivariate logistic regression model, BDNF emerged as a strong independent protective factor against depression (OR = 0.12, 95% CI: 0.05–0.29)." (PMID 40823578, 2025). "BDNF plays a significant role in the pathophysiology of depression and is considered a potential biomarker for its diagnosis." (PMID 40001468, 2025). "It was reported that with the alleviation of the depression, the level of the BDNF would enhance as well." (PMID 39796425, 2025). "For depression, they re-establish normal relations in mood-depressing areas by repairing glutamate levels and activating BDNF, a brain growth factor of significance." (PMID 40941042, 2025). "The BDNF/tropomyosin receptor kinase B (TrkB) signaling axis is another core regulator of neuroplasticity that shows evidence of dysregulation in depression." (PMID 41425661, 2025). "Levels of brain-derived neurotrophic factor (BDNF) and other neurotrophic factors are often reduced in individuals with depression and can be further affected by antidepressant treatment." (PMID 39377784, 2025). "Genes like Oprm1 and BDNF, which exhibited significant differential expression and strong functional relevance in the neurobiology of depression, emerged as potential molecular indicators." (PMID 40656047, 2025). "BDNF alters depression by remodeling in the hippocampus; upstream of that are actions of peroxisome proliferator-activated receptor (PPAR)α at PXR to drive increases in mitochondrial activity and, thereby neurosteroidogenesis to allopregnanolone." (PMID 39940941, 2025). "Conversely, reduced astrocytic BDNF expression has been observed in models of depression and chronic stress, further linking impaired glial trophic support to the development of affective disorders." (PMID 41462664, 2025). "Physical exercise enhances the activity of antioxidant enzymes and increases BDNF levels; elevated BDNF, in turn, promotes neuroplasticity, neuronal growth, and differentiation, thereby effectively improving mood and alleviating anxiety and depression." (PMID 41030341, 2025). "The increase in BDNF levels can enhance memory, contributing to the improvement of hippocampal function in individuals with depression." (PMID 41477617, 2025). "In 72 Polish postmenopausal participants, higher levels of BDNF and Geriatric Depression Scale (GDS) were observed, as were the clock test results in current and overweight participants." (PMID 40871684, 2025). "Intravenous administration of esketamine during surgery can elevate postoperative BDNF levels in parturients, thereby alleviating postoperative depression." (PMID 41403442, 2025). "Generally, BDNF is treated as a sufficient marker of neuroplasticity and is widely used in studies investigating depression and other topics for which neuroplasticity is relevant." (PMID 39613915, 2025). "Compared analysis of subclinical atherosclerosis markers, inflammatory profile, and BDNF production in patients with depression, bipolar affective disorder, and controls." (PMID 40313235, 2025). "Chronic inflammation and oxidative stress—prevalent in depression and aging—suppress BDNF expression, establishing a cascade of inflammation → reduced BDNF → clinical symptoms." (PMID 40871684, 2025).